RN7SL238P (RNA, 7SL, cytoplasmic 238, pseudogene)
Gene: Miscellaneous RNA gene on chromosome 15 (28,387,196 to 28,387,485, forward strand). Ensembl gene ENSG00000276891.
Homologues: Orthologues: pig Metazoa_SRP (54% identical), macaque Metazoa_SRP (48% identical). Paralogues in human: Metazoa_SRP (100% identical), RN7SL106P (100% identical), RN7SL536P (99% identical), RN7SL545P (99% identical), RN7SL759P (99% identical), RN7SL196P (88% identical), RN7SL286P (88% identical), RN7SL539P (88% identical), RN7SL796P (88% identical), RN7SL214P (79% identical), RN7SL736P (79% identical), RN7SL209P (78% identical), and 700 more.